MEG3 (maternally expressed 3)
Diseases named in the same sentence as MEG3 in open-access papers (continued):
Sharing a sentence is not in itself a finding about the gene and the disease.
dyslipidemia (2 papers, 2025 to 2026). "Taken together, our results demonstrate a link of MEG3 gene variants with dyslipidemia and neuropathic conditions in diabetic patients in a gender-specific manner." (PMID 40765563, 2025). "Moreover, association between rs7158663 genotypes and LDL-cholesterol levels was observed in female DN patients, revealing a correlation of MEG3 gene polymorphisms with dyslipidemia and neuropathic conditions in diabetic patients in a gender-specific manner." (PMID 40765563, 2025). "Measure maternally expressed gene 3 (MEG3) and microRNA-147b in serum of patients with and without dyslipidemia compared to healthy control." (PMID 42156472, 2026). "Serum expression levels of MEG3 and microRNA-147b, as non-coding RNA biomarkers, were measured across four equally subcategorized groups (patients with and without dyslipidemia (N = 66) and healthy controls with and without dyslipidemia (N = 66) using Polymerase Chain Reaction (PCR)." (PMID 42156472, 2026).
genitourinary cancers (2 papers, 2019 to 2025). "This comprehensive review explores the multifaceted functions of MEG3 in the context of genitourinary cancers through unravelling the molecular mechanisms underlying the influence of MEG3 on cellular proliferation, apoptosis, invasion, and metastasis." (PMID 40242248, 2025). "Upon examining the tumour-suppressive roles of lncRNAs in genitourinary cancers, MEG3 has emerged as a notable candidate." (PMID 40242248, 2025). "This review provides a comprehensive overview of the emerging roles of the tumor suppressor MEG3 in the genitourinary cancers, positioning it as a promising therapeutic target." (PMID 40242248, 2025). "By overcoming these barriers, MEG3 could significantly improve outcomes for patients with genitourinary cancers and pave the way for its integration into precision oncology." (PMID 40242248, 2025). "Summarizes the functions of MEG3 across genitourinary cancers." (PMID 40242248, 2025). "Collectively, these findings have propelled MEG3 into the spotlight as a target for therapeutic interventions, encouraging the need for well-designed clinical trials to evaluate its efficacy and safety in patients with genitourinary cancers." (PMID 40242248, 2025). "However, while MEG3’s tumor suppressive functions are well-documented in genitourinary cancers, its potential as a standalone therapy remains underexplored and requires further investigation." (PMID 40242248, 2025). "Additionally, we discuss the potential clinical implications of MEG3 as a biomarker and therapeutic target in genitourinary cancers." (PMID 40242248, 2025).
gynecological cancers (2 papers, 2021 to 2024). "In this article, we present a summary of the progress on ascertaining the biological functions of five lncRNAs (HOTAIR, NEAT1, H19, MALAT1, and MEG3) in female-oriented cancers, including breast and gynecological cancers, with the perspective of carcinogenesis, cancer proliferation, and metastasis." (PMID 34885213, 2021). "Therefore, in this article, we highlight the role of various lncRNAs and specifically five lncRNAs—HOTAIR, NEAT1, H19, MALAT1, and MEG3—in cancers unique to women, including breast and gynecological cancers." (PMID 34885213, 2021). "We further provide various perspectives on the association of some lncRNAs, i.e., HOTAIR, NEAT1, H19, MALAT1, and MEG3, in terms of invasion, proliferation, metastasis, apoptosis, and drug resistance of breast and gynecological cancers based on recent discoveries." (PMID 34885213, 2021).
head and neck cancer (2 papers, 2021). A primary or metastatic malignant neoplasm affecting the head and neck. "Additionally, recent studies have demonstrated the pro‐apoptotic effect of MEG3 on head and neck cancers." (PMID 33332708, 2021).
head and neck squamous cell carcinoma (2 papers, 2020 to 2024). A squamous cell carcinoma that arises from any of the following anatomic sites: lip and oral cavity, nasal cavity, paranasal sinuses, pharynx, larynx, and salivary glands. "Also, we explored the interactions of MEG3, miR‐421, and E‐cadherin in head and neck squamous cell carcinoma (HNSCC) tissues and cells." (PMID 32277605, 2020). "However, the downstream mechanism of MEG3 in regulating the molecular mechanism of epithelial‐mesenchymal transformation (EMT) in head and neck squamous cell carcinoma (HNSCC) progression demands further investigation." (PMID 32277605, 2020).
injury (2 papers, 2021 to 2022). Damage inflicted on the body as the direct or indirect result of an external force, with or without disruption of structural continuity. "The long noncoding RNA MEG3 is able to sponge microRNA-7b to upregulate the expression of NLRP3 to promote the aggravation of acute lung injury." (PMID 35547731, 2022). "The lncRNA MEG3 can recruit PTBP1 to regulate small heterodimer partner mRNA stability and cholestatic liver injury." (PMID 34706749, 2021).
Kaposi's sarcoma (2 papers, 2021 to 2022). A malignant neoplasm characterized by a vascular proliferation which usually contains blunt endothelial cells. "Of note, our bioinformatics analysis also demonstrated that Anril, Hotair, Malat1, Kcnq1ot1, and Meg3 regulate genes from the Kaposi sarcoma-associated herpes virus infection (KSHV) pathway." (PMID 33815273, 2021). "Kaposi’s sarcoma-associated HSV-encoded miRNAs have been shown to affect the expression of host lncRNAs such as Maternally Expressed 3 (MEG3), antisense non-coding RNA in the INK4 locus (ANRIL), and Urothelial Cancer Associated 1 (UCA1) in favor of cancer development." (PMID 35055001, 2022).
lentivirus infection (2 papers, 2024). Virus diseases caused by the Lentivirus genus. "After lentivirus infection, MEG3 was quantified using immunofluorescence and RT-qPCR." (PMID 38827318, 2024).
lipid metabolic disorders (2 papers, 2024 to 2025). "Our study demonstrated that lncRNA MEG3 regulates de novo lipogenesis by decreasing the expression and nucleus translocation of FOXO1 in HepG2 cells, suggesting that lncRNA MEG3 could be a promising therapeutic target in lipid metabolic disorders." (PMID 38713402, 2024).
liver diseases (2 papers, 2017 to 2024). "Considering the functional pattern of Meg3, we may conclude that lncRNA 2900097C17Rik is an inhibitory regulator of inflammation in macrophage but up regulated in liver disease." (PMID 29383134, 2017). "Another two candidates, lncRNA MEG3 and 2900097C17Rik that expressed conversely may explain the protective property of macrophage in the occurrence and development of liver disorders." (PMID 29383134, 2017).
low grade glioma (2 papers, 2021 to 2023). A grade I or grade II glioma arising from the central nervous system. "In low-grade glioma, MEG3 expression has been negatively correlated with the amounts of infiltrating B, CD8+ T and CD4+ T cell populations as well as macrophage, neutrophil, and dendritic cells." (PMID 37907501, 2023).
lymphoblastic lymphoma (2 papers, 2019 to 2020). A lymphoma composed of immature small to medium-sized precursor lymphoid cells (lymphoblasts). "MEG3 can inhibit the growth of lymphoblastic lymphoma through the miRNA‐214/AIFM2 axis." (PMID 32277605, 2020). "MEG3 can regulate the miR-214/AIFM2 axis to inhibit the growth of lymphoblastic lymphoma." (PMID 31531526, 2019).
mesothelioma (2 papers, 2018 to 2023). A usually malignant and aggressive neoplasm of the mesothelium which is often associated with exposure to asbestos. "Nine noncoding RNAs (Fendrr, Gm26902, Gm17501, Meg3, miR 17–92 cluster, Dubr, and Firre) were specifically elevated in mesothelioma tumors and shown to contribute to the heterogeneity of human mesothelioma." (PMID 36755350, 2023).
metastasis (2 papers, 2017 to 2019). The spread or migration of cancer cells from one part of the body (where they first appeared) to another. "LncRNA LINC00152, HEGBC, MALAT1 and ROR showed a marked correlation with positive lymph node metastasis (LNM), while lncRNA GCASPC, MEG3, LET and UCA1 had the opposite effect." (PMID 31297033, 2019).
Myelodysplasia (2 papers, 2018 to 2020). Clonal hematopoietic stem cell disorders characterized by dysplasia (ineffective production) in one or more hematopoietic cell lineages, leading to anemia and cytopenia. "Therefore, we investigated the expression activity within the DLK1–DIO3 region in the context of the methylation status of the MEG3-DMR in myelodysplasia." (PMID 30223454, 2018). "We investigated DNA methylation in the same regions (located in the MEG3-DMR) that were hypermethylated in APL so that we could compare methylation status in APL and myelodysplasia." (PMID 30223454, 2018). "Other mechanisms besides hypermethylation of the MEG3-DMR, such as the influence of transcription factors, may also play yet unrecognized roles in the regulation of the DLK1–DIO3 region in myelodysplasia." (PMID 30223454, 2018). "In addition, overexpression of the DLK1-DIO3 region, which harbours a large miRNA cluster and MEG3 (lncRNA) gene promoter, was observed in 50% of patients before treatment with AZA, and this was in conjunction with the diagnosis of AML with myelodysplasia-related changes." (PMID 33114584, 2020).
myelofibrosis (2 papers, 2015 to 2018). A partial or complete replacement of the bone marrow stroma by fibrous tissue. "Interestingly, MEG3 overexpression has also been detected in CD34+ cells from patients with primary myelofibrosis (found in 65% of patients), and this upregulation was related to increased blast counts and higher percentages of circulating CD34+ cells." (PMID 30223454, 2018).
myocarditis (2 papers, 2020 to 2023). Myocarditis is a condition that is characterized by inflammation of the heart muscle (myocardium). "The results from H&E staining showed that myocarditis in VMC mice was markedly ameliorated following MEG3 down‐regulation." (PMID 33047847, 2020). "Previous studies have reported that MEG3 can bind to miR‐223 and inhibit the expression of miR‐223 expression and that miR‐223 is down‐regulated in mice with myocarditis." (PMID 33047847, 2020). "Therefore, down‐regulation of MEG3 alleviated myocarditis by up‐regulating miR‐223 and inhibiting TRAF6." (PMID 33047847, 2020). "Down‐regulations of MEG3 or TRAF6 or up‐regulation of miR‐223 was observed to increase mouse weight, survival rate, LVEF and LVFS, while inhibiting myocarditis and inflammation via the NF‐κB pathway inactivation in VMC mice." (PMID 33047847, 2020). "Based on the finding that MEG3 regulates TRAF6 by binding to miR‐223, we wished to explore whether miR‐233 and TRAF6 are involved in the mediation of myocarditis by MEG3." (PMID 33047847, 2020). "In this study, we constructed a VMC model by infecting mice with CVB3, and then showed that inhibition of MEG3 could suppress the NF‐κB pathway as well as increase M2 macrophage transition through miR‐223‐mediated down‐regulation of TRAF6, therefore, ameliorating myocarditis in the VMC mice." (PMID 33047847, 2020).
peripheral nerve injury (2 papers, 2020 to 2023). Injury to a peripheral nerve. "MEG3 is also involved in the process of peripheral nerve injury." (PMID 37907501, 2023). "Our findings suggest that MEG3 or other lncRNAs may be a promising therapeutic target for peripheral nerve injury." (PMID 32436312, 2020).
pulpitis (2 papers, 2022 to 2024). Inflammation of the dental pulp. "It is interesting that lncRNAs can be packaged and delivered by extracellular vesicles, establishing a system of communication and regulation among cells, and it was suggested that the lncRNA MEG3 can be a cargo molecule in vesicles generated in an in vitro model of pulpitis." (PMID 39769365, 2024). "MEG3 lncRNA has been demonstrated as a negative regulator in the pulpitis process." (PMID 35711564, 2022). "Thus, lncRNA MEG3 appears to be important in the regulation of biological effects during pulpitis." (PMID 39769365, 2024). "MEG3 long noncoding RNA has been demonstrated as a negative regulator in the pulpitis." (PMID 35711564, 2022).
rectal cancer (2 papers, 2022 to 2024). A primary or metastatic malignant neoplasm that affects the rectum. "After MEG3 is downregulated in rectal cancer cells and MEG3 is restored, UPR response-related proteins, including GRP78, ATF6 and CHOP, are highly induced, and the cell apoptosis rate increases." (PMID 36523500, 2022).
sarcoma (2 papers, 2023). A usually aggressive malignant neoplasm of the soft tissue or bone. "CASC9, LINC00922, LINC00511, MEG3, MEG8, and SNHG16 were significantly related to the poor prognosis of sarcoma patients." (PMID 36816047, 2023).
serous ovarian cancer (2 papers, 2020 to 2022). "Here, we evaluated the potential of using the maternally expressed gene 3 (MEG3) tissue level as a prognostic marker in high-grade serous ovarian cancer (HGSOC), the most common and deadliest gynecologic malignancy." (PMID 32295169, 2020).
somatotroph tumors (2 papers, 2022 to 2024). "While the lncRNA MEG3 is known to inhibit cell proliferation, two independent studies have reported the involvement of the lncRNA MEG3 in the development of somatotroph tumors." (PMID 36010855, 2022).
viral infection (2 papers, 2020 to 2022). "ADAR plays an important role in innate immunity against viral infection, and lncRNA MEG3 acts as the main regulator of ADAR." (PMID 36005145, 2022). "As the role of ADAR as a controlling element in cellular response to viral infection is paramount, its regulation by MEG3 and interactions with lncRNAs in SARS-CoV-2 infected cells may influence progression of the disease." (PMID 33224264, 2020).
abortion (1 paper, 2021). the ending of pregnancy by removing a fetus or embryo before it can survive outside the uterus. "Database analysis of GSE14722 (RNA-seq data of embryonic villi from 11 abortion patients) and GSE9984 (RNA-seq data of embryonic villi from 12 normal pregnant women) shows that MEG3 expression was significantly lower in aborted villous tissues than in normal villous tissues (P < 0.01)." (PMID 34238211, 2021).
acute lung injury (1 paper, 2020). A condition of lung damage that is characterized by bilateral pulmonary infiltrates (pulmonary edema) rich in neutrophils, and in the absence of clinical heart failure. "We aimed to elucidate the roles of the long non-coding RNA (lncRNA) maternally expressed gene 3 (MEG3)/microRNA-7b (miR-7b)/NLR pyrin domain containing 3 (NLRP3) axis in lipopolysaccharide (LPS)-induced acute lung injury (ALI)." (PMID 32852284, 2020).
acute lymphoblastic leukemia (1 paper, 2023). Leukemia with an acute onset, characterized by the presence of lymphoblasts in the bone marrow and the peripheral blood. "MEG3-lncRNA expression has been suggested as a potential biomarker for therapy response and survival profile in childhood acute lymphoblastic leukemia (cALL), whereas encompasses miRNAs and promoter regions of miRNA species." (PMID 37486375, 2023).
alcoholic cirrhosis (1 paper, 2018). "Our data also indicated a reduction in MEG3 expression in patients with alcoholic cirrhosis compared with healthy controls." (PMID 30282972, 2018). "Compared with healthy controls, liver MEG3 was obviously downregulated in CHB patients as well as patients with alcoholic cirrhosis." (PMID 30282972, 2018).
Anxiety (1 paper, 2017). Intense feelings of nervousness, tension, or panic often arise in response to interpersonal stresses. "In this assessment, mice treated with si-MEG3 showed a higher velocity and spent more time in the center area of the apparatus than mice treated with si-s-MEG3, indicating an improved locomotor activity and anxiety-like behavior." (PMID 29238035, 2017).
brain injury (1 paper, 2018). Acute and chronic (see also brain INJURIES, CHRONIC) injuries to the brain, including the cerebral hemispheres, CEREBELLUM, and brain STEM. "Maternally expressed gene 3 (MEG3) was observed to be up-regulated in IS, acting as a competing endogenous RNA for miR-181b to regulate ischemic brain injury." (PMID 30579356, 2018).
cardiac interstitial fibrosis (1 paper, 2022). "Additionally, Wisper, CHRF, AK081284, MEG3 and MIAT are also important pro-fibrotic lncRNAs in cardiac interstitial fibrosis and act via diverse regulatory mechanisms." (PMID 36384975, 2022).
cervical adenocarcinoma (1 paper, 2022). An adenocarcinoma arising from the cervical epithelium. "Functional analysis experiments indicated that MEG3 promoted the sensitivity of cervical adenocarcinoma cells and drug-resistant cells to cisplatin." (PMID 36344947, 2022). "Moreover, MEG3 expression was significantly lower in cervical adenocarcinoma cisplatin-resistant cell lines." (PMID 36344947, 2022). "However, whether Lnc RNA MEG3 is involved in chemoresistance in cervical adenocarcinoma has not been reported." (PMID 36344947, 2022).
chronic hepatitis C (1 paper, 2018). "However, the clinical significance of liver MEG3 in CLDs patients including chronic hepatitis C patients needs further verification and analysis in large samples." (PMID 30282972, 2018).
cleft palate (1 paper, 2022). Cleft palate is a fissure type embryopathy that affects the soft and hard palate to varying degrees. "MEG3 is also strongly expressed during palatogenesis; its inhibition by proliferation of palatal mesenchymal cells involved in the TGF-β/Smad pathway can result in cleft palate in mouse fetuses exposed to TCDD." (PMID 35216185, 2022).
colitis (1 paper, 2023). Inflammation of the colon. "In our colitis mouse model, we did not observe any impact of M2-EV treatment on levels of the Meg3 and Creb1 gene in colon tissues." (PMID 37770932, 2023).
colon adenocarcinoma (1 paper, 2019). "The expression levels of maternally expressed gene 3 (MEG3), a known lncRNA, were markedly downregulated in colon adenocarcinoma (COAD) as observed in the TCGA database (P < 0.05)." (PMID 31729423, 2019).
colonic adenoma (1 paper, 2021). "Notably, the sponging correlation among Meg3, miR-708, and SOCS3 were present in a colonic adenoma mouse model and in clinical CRC tissues." (PMID 34934045, 2021).
colorectal tumors (1 paper, 2021). "Targeting of Meg3 and miR-708 might represent a promising strategy in both the diagnosis and therapy of colorectal tumors." (PMID 34934045, 2021).
Crohn disease (1 paper, 2022). A gastrointestinal disorder characterized by chronic inflammation involving all layers of the intestinal wall, noncaseating granulomas affecting the intestinal wall and regional lymph nodes, and transmural fibrosis. "In this study, we analyzed the expression of MEG3 and miR-181b in the peripheral blood of patients of Crohn’s disease to explore the effect of rs7158663 and rs322931." (PMID 35422450, 2022).
disc degeneration (1 paper, 2025). "Additionally, lncRNAs like HOTAIR and MEG3 have been implicated in disc degeneration, with HOTAIR promoting ECM degradation and apoptosis, while MEG3 offers protective effects by inhibiting MMP expression." (PMID 40688090, 2025).
ductal carcinoma (1 paper, 2015). "We found that MEG3 is expressed at significantly lower levels ininvasive ductal carcinoma than in normal breast tissue." (PMID 26205790, 2015).
encephalitis (1 paper, 2023). An acute inflammatory process affecting the brain parenchyma. "For the first time, this study implied a differential expression of Meg3, a long noncoding RNA, in hippocampal interneurons from mice with anti‐NMDAR encephalitis." (PMID 36942475, 2023).
Epiphora (1 paper, 2021). Abnormally increased lacrimation, that is, excessive tearing (watering eye). "Immunofluorescence data showed that in GC-1 cells, MEG3 overexpression significantly promoted NLRP3 and caspase-1 expression, indicating that it promoted epiphora, while silencing MEG3 significantly inhibited epiphora." (PMID 34222244, 2021).